DUSP22 (dual specificity phosphatase 22)
Diseases named in the same sentence as DUSP22 in open-access papers (continued):
Sharing a sentence is not in itself a finding about the gene and the disease.
lung carcinoma (3 papers, 2020 to 2024). "Exogenous DUSP22 expression was found to inhibit colony formation in multiple lung cancer cell lines, including HCC827, H1650, and LL/2, indicating a suppressive role of DUSP22 in lung tumorigenesis." (PMID 38877005, 2024). "Our study showed that DUSP22 acts as an EGFR phosphatase in lung cancer cells, inhibiting EGFR activity and its crosstalk with c-Met." (PMID 38877005, 2024). "Here, we investigated the role of DUSP22 in lung cancer development by studying its function in suppressing hyperactive EGFR signaling, a key oncogenic driver in LUAD." (PMID 38877005, 2024). "In summary, our study has provided insights into the tumor-intrinsic mechanisms of DUSP22 in suppressing lung cancer via EGFR." (PMID 38877005, 2024). "Next, we conducted colony formation assays to investigate the impact of DUSP22 deletion on the tumorigenicity of HCC827 lung cancer cells in response to gefitinib." (PMID 38877005, 2024). "Knockdown of DUSP22 using shRNA enhances EGFR dependency in HCC827 lung cancer cells and increases sensitivity to gefitinib, an EGFR inhibitor." (PMID 38877005, 2024). "Collectively, our data support a role for DUSP22 in the suppression of tumor development in lung cancer cells through the dephosphorylation of key target kinases in the EGFR signaling pathway." (PMID 38877005, 2024). "Exogenous DUSP22 expression reduces the colony-forming capacity of lung cancer cells and inhibits xenograft tumor growth primarily by targeting EGFR and suppressing its activity through dephosphorylation." (PMID 38877005, 2024). "Enforced DUSP22 expression significantly suppresses the growth of erlotinib-resistant H1650 lung cancer cell-based tumor by inhibiting EGFR and downstream ERK1/2 while not affecting sustained Akt activity." (PMID 38877005, 2024). "DUSP22 deletion in lung cancer cells increases dependence on EGFR activity for growth and survival, as it leads to co-activation of EGFR and ERK1/2." (PMID 38877005, 2024). "Here, we have developed a working model demonstrating that DUSP22 negatively regulates cell growth and migration in lung cancer cells through EGFR/c-Met and PD-L1-dependent pathways." (PMID 38877005, 2024). "In contrast, DUSP22 deletion enhances HCC827 cell sensitivity to gefitinib, suggesting that DUSP22 loss promotes EGFR dependence in lung cancer, and targeting EGFR could be a more effective therapeutic approach for DUSP22-deficient lung tumors." (PMID 38877005, 2024). "Additionally, lentiviral deletion of DUSP22 by shRNA enhances lung cancer cell migration through EGFR/c-Met and PD-L1-dependent pathways." (PMID 38877005, 2024). "In addition, DUSP22 deletion induces PD-L1 upregulation in lung cancer cells, as confirmed by FACS analysis." (PMID 38877005, 2024). "This implies that constitutively-active EGFR mutants can promote lung cancer cell migration, partly through the enhanced EGFR activity resulting from DUSP22 deletion." (PMID 38877005, 2024). "In this regard, DUSP22, a member of the DUSP1 family which reduces JNK activation, negatively regulates cell migration through FAK dephosphorylation and inactivation in lung cancer cells." (PMID 33800291, 2021). "Based on these findings, it is reasonable to explore whether the same regulatory connection between DUSP22 and EGFR plays a significant role in repressing the development and progression of EGFR-driven lung cancer." (PMID 38877005, 2024). "Importantly, our data revealed a consistent dephosphorylation-based regulation between DUSP22 and EGFR in different lung cancer cell lines harboring wild-type (WT) or mutant EGFR genes." (PMID 38877005, 2024). "EGFR was identified as the primary target of DUSP22 in both HCC827 and H1650 lung cancer cells." (PMID 38877005, 2024). "Prior research has shown that DUSP22 can inhibit the migration of H1299 lung cancer cells with wild-type EGFR by dephosphorylating FAK, a non-receptor tyrosine kinase." (PMID 38877005, 2024).
lung carcinoma (continued). "Furthermore, PARG depletion via siRNA was reported to be synthetic lethal with dual specificity phosphatase 22 (DUSP22) via suppression of the mTOR/PI3k/AKT and an increase in the expression of PUMA inducing increased apoptosis in lung cancer." (PMID 33005627, 2020). "The interplay of DUSP22 with EGFR and PD-L1 in lung cancer cells remains unclear." (PMID 38877005, 2024). "Considering the dephosphorylation function of DUSP22, we performed a phosphokinase array to identify kinases in both HCC827 (gefitinib-sensitive) and H1650 (gefitinib-resistant) lung cancer cells in the presence or absence of DUSP22 shRNA (± gefitinib for HCC827)." (PMID 38877005, 2024). "Significantly, DUSP22 failed to inhibit colony formation in EGFRlow H520 and TC-1 cells, suggesting that DUSP22 predominantly acts on EGFR and hinders EGFR signaling to impede lung cancer cell proliferation via dephosphorylation, regardless of their EGFR mutation status." (PMID 38877005, 2024).
lupus nephritis (3 papers, 2016 to 2023). Glomerulonephritis in the context of systemic lupus erythematosus. "The pathogenic role of DUSP22-deficient T cells in SLE nephritis has been demonstrated by characterizing T-cell-specific DUSP22 dominant-negative transgenic (Lck-DUSP22-C88S Tg) mice." (PMID 31766293, 2019). "Furthermore, DUSP22 dysregulation is associated with human lupus nephritis." (PMID 36765305, 2023). "Moreover, downregulation of DUSP22 protein in T cells is a prognostic biomarker for SLE nephritis." (PMID 36765305, 2023).
asthma (2 papers, 2019 to 2022). "The genes associated with the largest difference in DNA methylation between cells isolated from individuals with asthma versus those without asthma (pronase, DUSP22; bronchial brush, WNT7B) have links to asthma pathogenesis." (PMID 31595000, 2019).
autism (2 papers, 2018 to 2022). Persistent deficits in social interaction and communication and interaction as well as a markedly restricted repertoire of activity and interest as well as repetitive patterns of behavior. "KMT2C, DUSP22 and miR-335 are autism susceptibility genes and miRNAs." (PMID 29523860, 2018). "The physiological role of DUSP22 in the brain is unclear, and a rare DUSP22 deletion was found in a patient with autism and mild intellectual disability." (PMID 29523860, 2018).
peripheral T-cell lymphoma (2 papers, 2016 to 2024). "Monoallelic 6p25.3 rearrangements associated with DUSP22 (Dual Specificity Phosphatase 22) gene silencing have been reported in CD30+ peripheral T-cell lymphomas (PTCL), mostly with anaplastic morphology and of cutaneous origin." (PMID 27626696, 2016). "Recent advancements in molecular diagnostics, such as testing for DUSP22 and TP63 rearrangements, could offer valuable insights into ALK-negative ALCL prognosis and aid in distinguishing it from peripheral T-cell lymphoma (PTCL) NOS." (PMID 39610919, 2024).
psoriasis (2 papers, 2023 to 2025). An autoimmune condition characterized by red, well-delineated plaques with silvery scales that are usually on the extensor surfaces and scalp. "Another DMP separating “all” psoriasis patients from controls was DUSP22, encoding for a protein phosphatase responsible for activation of the c-Jun NH2-terminal kinase (JNK) signaling pathway that is dysregulated in psoriasis, SLE and ankylosing spondylitis." (PMID 37662940, 2023). "Serum DUSP22 levels are decreased in patients with psoriasis and negatively correlate with the psoriasis area severity index." (PMID 39944077, 2025).
T cell lymphoma (2 papers, 2019 to 2024). "In T-cell lymphomas, monoallelic 6p25.3 alterations cause down-regulation of the dual specificity phosphatase 22 (DUSP22) protein." (PMID 39221352, 2024). "In addition, the reduced expression of DUSP22 has been associated with T cell lymphoma subtypes, where silenced DUSP22 expression and hypomethylation of the DUSP22 promoter were found." (PMID 31159473, 2019). "Recent cases of various DUSP22 rearranged T-cell lymphomas with features spanning a spectrum from LyP to MF to pcALCL have been described." (PMID 39221352, 2024).
B-cell lymphoma (1 paper, 2018). "Likewise, rearrangements disrupting the dual specificity phosphatase gene DUSP22 are associated with T-cell and B-cell lymphoma, consistent with our finding of a positive association between methylation at DUSP22 and mature B-cell neoplasm." (PMID 29310692, 2018).
B-cell neoplasm (1 paper, 2018). A group of heterogeneous lymphoid tumors generally expressing one or more B-cell antigens or representing malignant transformations of B-lymphocytes. "Interestingly, elevated methylation in a cluster of eight CpG sites at DUSP22 was associated with increased risk of mature B-cell neoplasm yet reduced risk of urothelial cell carcinoma." (PMID 29310692, 2018).
celiac disease (1 paper, 2019). An autoimmune genetic disorder with an unknown pattern of inheritance that primarily affects the digestive tract. "Interestingly, previous GWAS studies have identified genetic variants near the DUSP22 gene associated with IBD and celiac disease." (PMID 31185018, 2019).
chromophobe renal cell carcinoma (1 paper, 2021). Chromophobe renal cell carcinoma is a rare subtype of renal cell carcinoma, originating from the intercalating cells of the collecting ducts and macroscopically manifesting as a well-circumscribed, highly lobulated, solid tumor that is usually diagnosed at an early stage. "Therefore, DUSP22 may regulate cancer invasion in other forms of RCC, such as papillary renal cell carcinoma and chromophobe renal cell carcinoma." (PMID 34207247, 2021).
cognitive decline (1 paper, 2021). "DUSP22 and RPL37 associated with rate of cognitive decline as measured by the slope of mPACC, and AMPD3 associated with the slope of CDR-SB and MCI to AD conversion status are also abundantly expressed in microglia." (PMID 34654479, 2021).
deafness (1 paper, 2020). An inherited or acquired condition characterized by the complete loss of the ability to hear from one or both ears. "Relevant to the symptoms of tinnitus, deletions of the DUSP22 gene in humans results in severe intellectual disability and deafness, while CYP2E1 is integral to the metabolism of acrylonitrile, which has been shown in rodents to potentiate damage to hair cells in the inner ear." (PMID 33192958, 2020).
dyslipidemia (1 paper, 2022). "The expression of DUSP22 considerably ameliorated PO-stimulated dyslipidemia in hepatocytes, but this effect was completely abolished when DUSP22-C88S was mutated." (PMID 36209205, 2022).
eye cancer (1 paper, 2022). "In particular, retinal density– and FD-lowering alleles at several PoPS-prioritized genes showed associations with higher risk of skin neoplasms, malignant melanoma, and eye cancer (IRF4/DUSP22, SLC45A2); a separate set of loci showed associations with lighter skin color (GNB2, ACTG1)." (PMID 34743558, 2022).
Hepatic steatosis (1 paper, 2022). Steatosis is a term used to denote lipid accumulation within hepatocytes. "Here, the authors show that ROS-mediated DUSP22 degradation participates in the progression of fatty liver, contributing to the development of NASH and associated HCC via regulating FAK and its downstream ERK1/2 and NF-κB signaling cascade." (PMID 36209205, 2022). "Collectively, these observations illustrated that DUSP22 protected against hepatic steatosis through mediating NF-κB, ERK1/2, and FAK signaling pathways." (PMID 36209205, 2022). "Hepatic steatosis stimuli TGF-β1 strongly downregulated DUSP22 expression in L02 cells, indicating the potential involvement of DUSP22 during fibrosis." (PMID 36209205, 2022). "Subsequently, DUSP22HepKO mice were subjected to a 24-week HFHC feeding to investigate whether DUSP22 ablation contributed to hepatic steatosis progression." (PMID 36209205, 2022). "Hepatocyte-specific DUSP22 knockout markedly hastened the development of NASH and HCC in multiple mouse models by facilitating liver steatosis, inflammation, and fibrosis; however, DUSP22 overexpression in hepatocytes dramatically relieved the severe progression of NASH and related HCC in mice." (PMID 36209205, 2022). "According to our current findings, previous studies, and the characteristic of DUSPs family, we demonstrated that the dephosphorylating capacity of DUSPs family members (DUSP22, DUSP3, DUSP9, DUSP12, DUSP14, DUSP26, etc) might be indispensable for its protective role against hepatic steatosis." (PMID 36209205, 2022).
Insulin resistance (1 paper, 2023). Increased resistance towards insulin, that is, diminished effectiveness of insulin in reducing blood glucose levels. "Here, we checked the association of DNA methylation levels at CpG sites located in the DUSP22 promoters in adipose tissue for several metabolic phenotypes (BMI, visceral fat, insulin resistance, fasting blood glucose, incident T2D) in a 450 k methylation dataset from 538 female twins." (PMID 36715159, 2023).
kidney cancer (1 paper, 2021). Primary or metastatic malignant neoplasm involving the kidney. "We found that five aging-related genes (DUSP22, MAPK14, MAPKAPK3, STAT1, and VCP) from kidney cancer patients were significantly related to patient survival." (PMID 34207247, 2021).
liver fibrosis (1 paper, 2022). "Among all these analyzed DUSPs, DUSP3, DUSP8, DUSP12, DUSP14, DUSP16, DUSP22, and DUSP26 were significantly decreased in the liver of NASH patients with obvious hepatocyte ballooning, severe inflammatory infiltrate, and pattern of liver fibrosis compared with the normal individuals." (PMID 36209205, 2022).
lung adenocarcinoma (1 paper, 2024). A carcinoma that arises from the lung and is characterized by the presence of malignant glandular epithelial cells. "Our study demonstrated that decreased DUSP22 expression is associated with shorter disease-free survival, advanced TNM (tumor, lymph nodes, and metastasis), cancer stage, and higher tumor grade in lung adenocarcinoma (LUAD) patients." (PMID 38877005, 2024).
lung squamous cell carcinoma (1 paper, 2024). "However, we did not observe a significant correlation between the expression of DUSP22 and the prognosis of lung squamous cell carcinoma (LUSC) patients." (PMID 38877005, 2024).
metastatic colorectal cancer (1 paper, 2022). "In this study that included 92 patients, patients with metastatic colorectal cancer and low expression of DUSP22 had a trend towards worse survival, although not statistically significant." (PMID 36295658, 2022).
nonalcoholic steatohepatitis (1 paper, 2025). "Earlier studies have shown that FAK deficiency significantly suppresses MET/CAT-driven hepatocarcinogenesis, In DUSP22-deficient tumors, FAK activation promotes the progression of nonalcoholic steatohepatitis–associated HCC." (PMID 41232667, 2025).
renal cell carcinoma (1 paper, 2021). "As a result, five aging-related genes (DUSP22, MAPK14, MAPKAPK3, STAT1, and VCP) in normal tissues were found to be significantly associated with a worse survival outcome in patients with renal cell carcinoma (RCC)." (PMID 34207247, 2021).
sarcopenia (1 paper, 2025). Progressive decline in muscle mass due to aging which results in decreased functional capacity of muscles. "In this study, DUSP22 was found to be upregulated in sarcopenia patients and models of skeletal muscle wasting." (PMID 40263624, 2025). "The DUSP22-JNK-FOXO3a axis could be exploited to treat sarcopenia or related aging disorders." (PMID 40263624, 2025).
spinal muscular atrophy (1 paper, 2017). A motor neuron disease that affect the muscles, and characterized by muscle weakness and atrophy resulting from progressive degeneration and irreversible loss of the anterior horn cells in the spinal cord (i.e., lower motor neurons) and the brain stem nuclei. "The splicing abnormalities of DUSP22 were shown to occur in spinal muscular atrophy motor neurons." (PMID 28902166, 2017).
spondylitis (1 paper, 2023). The inflammation of a vertebra. "In addition, inverse correlations of DUSP22 gene expression in peripheral T cells with C-reactive protein, erythrocyte sedimentation rate, and Bath Ankylosing Spondylitis Disease Activity Index (BASDAI) were observed (all p < 0.05)." (PMID 36765305, 2023).
T-cell leukemia (1 paper, 2016). A malignant disease of the T-lymphocytes in the bone marrow, thymus, and/or blood. "Restoring expression of the physiological DUSP22 isoform in the 1301 DUSP22-deficient T cell leukemia cell line enhanced apoptosis and strongly impaired both clonogenicity in soft agar and tumorigenicity in immuno-deficient mice." (PMID 27626696, 2016).
tauopathies (1 paper, 2017). "Whether DUSP22-mediated regulation of IL-6 has any implications in tauopathies may be an interesting topic for study, since it has already been shown that DUSP22 can influence tau phosphorylation via a protein kinase A-dependent pathway." (PMID 28902166, 2017).
urothelial cell carcinoma (1 paper, 2018). "Methylation at DUSP22 was also negatively associated with risk of urothelial cell carcinoma, reminiscent of situations in which the same genetic variant is associated oppositely with risk of different types of cancer." (PMID 29310692, 2018).